C1QB (complement C1q B chain)
Diseases named in the same sentence as C1QB in open-access papers (continued):
Sharing a sentence is not in itself a finding about the gene and the disease.
schizophrenia (3 papers, 2011 to 2024). A major psychotic disorder characterized by abnormalities in the perception or expression of reality. "In this context it is quite important to note that chromosomal region 1p36 carrying C1QB gene has already been associated with schizophrenia in two genome-wide linkage scans." (PMID 21951915, 2011). "The haplotype analysis, therefore, confirmed detected association of the C1QB rs291982 variant with schizophrenia." (PMID 21951915, 2011). "We also found the increased expression of component 4 (C4B) and C1QA and C1QB genes in male schizophrenia patients, which participate in inflammation and have been previously linked to schizophrenia vulnerability; meanwhile, increased C4 expression also prompts microglia-mediated engulfment in mice." (PMID 39068467, 2024). "The association between the C1QB rs291982*G genetic variant and schizophrenia obtained in our study may suggest the etiological significance of C1QB gene in schizophrenia in Armenian population." (PMID 21951915, 2011). "However, no data regarding association of C1Q encoding genes (C1QA and C1QB) polymorphisms to schizophrenia have been published yet." (PMID 21951915, 2011). "Importantly, the susceptibility for schizophrenia was particularly associated with C1QB rs291982 GG genotype (OR = 2.5, pcorrected = 9.6E-5)." (PMID 21951915, 2011). "Therefore, C1QB gene may be considered as a relevant candidate gene for susceptibility to schizophrenia." (PMID 21951915, 2011). "The results obtained suggest that C1QB gene may be considered as a relevant candidate gene for susceptibility to schizophrenia, and its rs291982*G minor allele might represent a risk factor for schizophrenia at least in Armenian population." (PMID 21951915, 2011). "In the present study four SNPs of the complement C1Q component genes (C1QA: rs292001, C1QB rs291982, rs631090, rs913243) were investigated in schizophrenia-affected and healthy subjects." (PMID 21951915, 2011). "Secondly, we did not reveal how the C1QB rs291982 SNP, significantly associated with schizophrenia in our study, alters the C1QB function." (PMID 21951915, 2011). "Also, the observed differences in the C1QB gene LD blocks between the patients with schizophrenia and control subjects may suggest that C1QB rs291982*G allele is a marker of a haplotype carrying "causative" variant located nearby on the first chromosome." (PMID 21951915, 2011).
tuberculosis (3 papers, 2022 to 2023). A chronic, recurrent infection caused by the bacterium Mycobacterium tuberculosis. "As to the other genes, C1QB also showed a reduction in expression after tuberculosis treatment." (PMID 38288122, 2023). "The specific mechanism of C1qB in tuberculosis needs to be further studied." (PMID 35345666, 2022). "However, in the present results, the C1QB gene obtained a significantly higher value of gene expression in the fluid of the non-TB group compared to the pleural tuberculosis group." (PMID 38288122, 2023).
yellow fever (3 papers, 2011 to 2024). "Consistent with our results, complements including C1QB were also found to be upregulated in blood cells early after yellow fever (YF17D) vaccination." (PMID 35686122, 2022). "C1QB, integral to the complement system, implicates inflammation regulation as a crucial process in both AKI and viral infections." (PMID 39027131, 2024). "An excellent example of this concept is the identification of a gene signature including C1QB and EIF2AK4, which correlated with and predicted CD8+ T cell responses to the yellow fever vaccine with a high degree of accuracy." (PMID 22241978, 2011).
amyotrophic lateral sclerosis (2 papers, 2018 to 2021). Amyotrophic lateral sclerosis (ALS) is a neurodegenerative disease characterized by progressive muscular paralysis reflecting degeneration of motor neurons in the primary motor cortex, corticospinal tracts, brainstem and spinal cord. "Grewal and colleagues found that C1qB mRNA increases in association with neurodegeneration in sporadic amyotrophic lateral sclerosis (ALS)." (PMID 33766068, 2021). "C1QB is also increased in sciatic nerves derived from Sh3tc2ΔEx1/ΔEx1 mice and complement activation at the motor end-plates in amyotrophic lateral sclerosis has been described as a disease modifier." (PMID 30562927, 2018).
C1Q deficiency (2 papers, 2012 to 2013). "We report herein a girl with C1q deficiency, and the identification of a novel splice site mutation in the C1qB gene, which is the first confirmed genetic mutation in a Japanese individual with C1q deficiency." (PMID 24160257, 2013).
colitis (2 papers, 2019 to 2023). Inflammation of the colon. "Whereas resident macrophage marker C1qb and C1qc were reduced in CD45+ cells from Il17b-/- colitis mice (P < 0.05)." (PMID 36814913, 2023).
colon cancer (2 papers, 2022 to 2024). "We also analyzed the relationship between C1QA, C1QB, C1QC and the survival of colon cancer patients, and the results showed that a high expression of C1QC in colon cancer patients led to a poor prognosis (p < 0.05)." (PMID 35765947, 2022). "Therefore, it is speculated that the expression levels of C1QA, C1QB, and C1QC are closely related to the development of colon cancer." (PMID 35765947, 2022).
colorectal cancer (2 papers, 2024). A primary or metastatic malignant neoplasm that affects the colon or rectum. "Subsequently, co-localization analysis of the C1QB gene and colorectal cancer tissue was performed to identify the expression quantitative trait locus (eQTL) associated with colorectal cancer." (PMID 39109334, 2024). "Using Mendelian randomization, the study identified C1QB as a risk factor for colorectal cancer (CRC) and a promising drug target." (PMID 39400959, 2024).
diabetic nephropathy (2 papers, 2023). "This bioinformatics analysis identified four disulfidptosis-related genes (CXCL6, CD48, C1QB, and COL6A3) with high diagnostic value and their expression may be closely related to the declined renal function in diabetic nephropathy." (PMID 38028597, 2023). "In addition, many researchers have also found that C1QB may be the pivotal gene in diabetic nephropathy." (PMID 38028597, 2023). "In the volcano plot, CXCL6, CD48, C1QB, and COL6A3 are all highly expressed in diabetic nephropathy patients, with areas under the ROC curve of 0.908, 0.928, 0.907, and 0.895, respectively." (PMID 38028597, 2023). "This study identified four key genes (CXCL6, CD48, C1QB, and COL6A3) involved in diabetic nephropathy using a series of bioinformatics methods." (PMID 38028597, 2023). "The intersection of the two algorithms obtained four key genes for diabetic nephropathy (CXCL6, CD48, C1QB, and COL6A3) which were used to construct the nomogram." (PMID 38028597, 2023). "Thus, monitoring CXCL6, CD48, C1QB, and COL6A3 expression can help in the diagnosis of diabetic nephropathy." (PMID 38028597, 2023). "Thus, CXCL6, CD48, C1QB, and COL6A3 may be involved in kidney function deterioration in diabetic nephropathy patients." (PMID 38028597, 2023). "The gradually decreasing glomerular filtration rate and increasing plasma creatinine with the increased expression of CXCL6, CD48, C1QB, and COL6A3 suggests that the deterioration of kidney function in diabetic nephropathy may be closely related to the expression of key genes." (PMID 38028597, 2023). "The expression of CXCL6, CD48, C1QB, and COL6A3 was higher in diabetic nephropathy patients than in normal controls, indicating that their expression is closely related to disease progression, so these key genes may be potential new therapeutic targets for diabetic nephropathy." (PMID 38028597, 2023).
diffuse large B-cell lymphoma (2 papers, 2022 to 2024). "Upregulation of C1QA, C1QB, and C1QC in peripheral T-cell lymphoma and upregulation of C1QC in Epstein-Barr Virus-positive diffuse large B-cell lymphoma have been reported previously." (PMID 36873459, 2022).
epilepsy (2 papers, 2016 to 2021). A brain disorder characterized by episodes of abnormally increased neuronal discharge resulting in transient episodes of sensory or motor neurological dysfunction, or psychic dysfunction. "C1QB has been found to be a epilepsy related gene and the expression of C1QB mRNA declines in brain peritumoral tissues of patients with tumor-induced epilepsy." (PMID 26742644, 2016). "Taken together, we proposed that complement system might play key roles in the development of epilepsy by dysregulating the expression of C1QB, C1S and CFI." (PMID 26742644, 2016). "According to other studies, C1QB is closely related to the brain tumor-induced epilepsy, whereas its specific role has not been discussed." (PMID 34915882, 2021). "The dysregulation of C1QB, C1S, CFI, SCN3B and FN1 may be used potential gene targets for epilepsy treatment." (PMID 26742644, 2016). "Additionally, C1QB, C1S, CFI, SCN3B and FN1 may be potential therapeutic targets for epilepsy." (PMID 26742644, 2016).
esophageal squamous cell carcinoma (2 papers, 2022 to 2023). Esophageal squamous cell carcinoma (ESCC) is a type of esophageal carcinoma (EC) that can affect any part of the esophagus, but is usually located in the upper or middle third. "We analyzed two single-cell RNA sequencing (scRNA-seq) datasets (GSE145370 and GSE160269) of esophageal squamous cell carcinoma to identify a novel TREM2-positive TAM subpopulation characterized by upregulation of TREM2, C1QC, C1QB, C1QA, SPP1, and APOE." (PMID 37187751, 2023).
head and neck squamous cell carcinoma (2 papers, 2019 to 2022). A squamous cell carcinoma that arises from any of the following anatomic sites: lip and oral cavity, nasal cavity, paranasal sinuses, pharynx, larynx, and salivary glands. "Interestingly, all five of these genes, CD74, C1QB, FCER1G, TYROBP, and C1QA are part of a protein-protein interaction network comprised of 20 proteins in total that are found only in head and neck squamous cell carcinomas but not in normal head and neck specimens." (PMID 31139325, 2019).
ischemic stroke (2 papers, 2021 to 2022). A stroke disorder caused by obstruction of blood flow to the brain, due to thrombotic (local blood clot formation) or embolic (due to a blood clot or other material traveling from another site) event. "Considering that C1R and C1QB are part of the C1 complex that initiates the classical pathway of the complement cascade, our results indicate that an abnormal complement status might be involved in the development of ischemic stroke." (PMID 34912031, 2021). "We revealed marked upregulation of four proteins (A2MG, C1QB, C1R, and HRG) in EVs enriched fractions by 7.3 ± 4.4 years before ischemic stroke onset, indicating their potential as biomarkers for predicting future ischemic stroke events." (PMID 34912031, 2021). "A2MG, C1QB, C1R, and HRG were found to be potential predictors of ischemic stroke development; however, further validation and investigation are necessary to determine the roles of all of these differentially expressed proteins in ischemic stroke development." (PMID 34912031, 2021). "In comparison to age- and sex-matched controls who did not develop any brain lesion, alpha-2-macroglobulin (A2MG), complement C1q subcomponent subunit B (C1QB), complement C1r subcomponent (C1R), and histidine-rich glycoprotein (HRG) were significantly upregulated in the ischemic stroke patients." (PMID 36140248, 2022). "Alpha-2-macroglobulin (A2MG), complement C1q subcomponent subunit B (C1QB), complement C1r subcomponent (C1R), and histidine-rich glycoprotein (HRG) were significantly upregulated by 2.21-, 2.15-, 2.24-, and 2.16-fold, respectively, in the ischemic stroke group as compared to the control group." (PMID 34912031, 2021).
lupus nephritis (2 papers, 2009 to 2023). Glomerulonephritis in the context of systemic lupus erythematosus. "Polymorphisms in the regulatory region of C1qb gene have been correlated with down-regulation of the murin c1q protein levels and linked to lupus nephritis." (PMID 19799787, 2009). "Since there are certain similarities between different kidney diseases, we explored the expression of key genes in different kidney diseases, finding that C1QB was highly expressed in lupus nephritis with the lowest expression in membranous glomerulonephropathy." (PMID 38028597, 2023).
mantle cell lymphoma (2 papers, 2022 to 2024). Mantle cell lymphoma is a rare form of malignant non-Hodgkin lymphoma affecting B lymphocytes in the lymph nodes in a region called the ``mantle zone''. "Complement C1qB Chain (C1QB, C+A− quadrant), Increased C1QB expression decreases the effectiveness of combined Ibrutinib and Venetoclax in patients with Mantle-Cell lymphoma (a B-cell lymphoma) and is associated with a worse prognosis." (PMID 39336806, 2024).
myopia (2 papers, 2017 to 2023). "Previous studies have reported the upregulation of the complement pathway, including C1q, C1qa, C2 and C1qb during the development stages of myopia in guinea pigs and chicks." (PMID 37448698, 2023). "A diverse range of complement-related genes were differentially-expressed, with components and regulators of both the classical and alternate pathways up-regulated in late myopia (CS1, PROS1, C1QB and CFD) and late hyperopia (SERPING1, C1QA, CRP, C7 and CFD)." (PMID 28852117, 2017).
Obesity (2 papers, 2024 to 2025). Accumulation of substantial excess body fat. "Similarly, the Complement Activation Network, characterized by increased C9 and CRP and decreased C1QB, aligned with the chronic low-grade inflammation observed in obesity." (PMID 40981199, 2025).
preeclampsia (2 papers, 2021 to 2023). Preeclampsia is a hypertensive disorder of pregnancy that is characterized by new-onset hypertension with proteinuria presenting after 20 weeks of gestation, and depending on mild or severe forms may initially present with severe headache, visual disturbances, and hyperreflexia. "Notably, the gene C1QB was also identified in the models, highlighting the imbalance of C1QB between healthy pregnancies and preeclampsia." (PMID 36849879, 2023). "M2 macrophages (CD136+MRC1+C1QA+C1QB+, P=0.007) and mast cells (TPSAB1, P=0.007) were decreased in early-onset preeclampsia samples, while M1 macrophages (CD86+MSR1+) were not altered based on gene expression." (PMID 34992598, 2021).
sporadic amyotrophic lateral sclerosis (2 papers, 2021 to 2024). Sporadic amyotrophic lateral sclerosis is a amyotrophic lateral sclerosis in which there is no known cause, such as no family history. "C1qb is one of the complement components and associated with various diseases, such as neuropathic pain, brain lesion, and sporadic amyotrophic lateral sclerosis." (PMID 38180614, 2024).
squamous cell carcinoma (2 papers, 2019 to 2022). A carcinoma arising from squamous epithelial cells. "The expression of C1QB in adenocarcinoma, squamous cell carcinoma, and adenosquamous carcinoma was also statistically different (p = 0.013)." (PMID 36313902, 2022).
amyloid (1 paper, 2023). "These genes, Thy1, Gfap, Tyrobp, Ctsd, Cst7, C1qb, Lyz2, Ctss, Trem2, Mpeg1, Hexb, Cd68, C1qb, C1qa, Ctsz, Grn, Laptm5, B2m, C1qc, Hexa, and Serpina3n, were increased in the 7-month-old 5XFAD model in the cortex and associated with amyloid plaque image patterns." (PMID 38036733, 2023).
Apathy (1 paper, 2025). Apathy is a quantitative reduction of interest, motivation and the initiation and persistence of goal-directed behavior, where often the accompanying emotions, thoughts, and social interactions are also diminished. "Composite apathy scores were strongly and positively correlated with mRNA fold changes for all examined genes: Tyrobp, Trem2, C1qa, C1qb, C1qc, C3, C3ar1, and Cd33 (p < 0.0001)." (PMID 41377997, 2025).
asthma (1 paper, 2021). "C1QB and HLA-DQA1 were overexpressed in the intestine, but were found to be reduced in asthma airways." (PMID 34332619, 2021).
Autoimmunity (1 paper, 2024). The occurrence of an immune reaction against the organism's own cells or tissues. "The complement system also plays a crucial role in SLE pathogenesis, particularly components such as C1QA, C1QB, C2, and C3, which are essential for clearing apoptotic debris and immune complexes, thereby reducing autoimmunity and systemic inflammation." (PMID 39717551, 2024).
cavernous hemangioma (1 paper, 2022). A hemangioma characterized by the presence of cavernous vascular spaces. "Among all types of cells in the cavernous hemangioma, only m2Maph highly expressed C1QA, C1QB, and C1QC, which provided a deeper understanding of the origin and functions of C1q in the immune responses." (PMID 35865633, 2022).
chronic kidney disease (1 paper, 2025). Impairment of the renal function secondary to chronic kidney damage persisting for three or more months. "Importantly, intrarenal complement gene expression (C1R, C1QB, C6, C9, C5, MASP2) predicts nonresponse to induction therapy, alluding to the potential pathogenic role of intrarenal complement gene expression in chronic kidney disease." (PMID 41031884, 2025).
colorectal tumors (1 paper, 2019). "Specifically, cytokines that were previously shown to correlate with the cytolytic index (C1QA, C1QB, C1QC, CXCL9, CXCL10, CXCL11 and CXCL13), were upregulated in CYT-high colorectal tumors." (PMID 31429779, 2019).
congenital cataracts (1 paper, 2023). "We identified 18 HUB genes, among which four core genes, C1qa, C1qb, C1qc, and Cd74, were closely related to congenital cataracts induced by Crim1 mutation." (PMID 36586009, 2023). "In conclusion, through comprehensive biological analysis of the GSE62561 gene expression profile, a total of 750 DEGs were identified, of which C1qa, C1qb, C1qc, and Cd74 may be related to the occurrence and development of congenital cataracts caused by Crim1 mutations." (PMID 36586009, 2023). "In addition, some researchers have found that the pathogenesis of congenital cataracts caused by TDRD7 deficiency may be related to the immune response, defence response, and related genes LY86, C1QA, C1QB, and C1QC." (PMID 36586009, 2023). "In this study, the C1qa, C1qb, and C1qc genes were upregulated in mutant mice, suggesting that the early development of congenital cataracts may activate the classical complement system, leading to synaptic disorders and neurodegenerative diseases, thus promoting the development of CC." (PMID 36586009, 2023).
Crohn disease (1 paper, 2024). A gastrointestinal disorder characterized by chronic inflammation involving all layers of the intestinal wall, noncaseating granulomas affecting the intestinal wall and regional lymph nodes, and transmural fibrosis. "We painted the landscapes of monocyte-macrophages and identified 5 distinct subsets including monocytes, C1QB+ macrophages, HSPA1B+ macrophages, IL-1B+ macrophages, and TMSB4X + macrophages in the intestinal mucosa from Crohn’s disease patients." (PMID 39095853, 2024).
cryptococcal infection (1 paper, 2022). "In particular, of the top 10 genes with the largest change in response to cryptococcal infection, three are components of the classical complement activation pathway: C1qb, C1qa, and C1qc." (PMID 35628686, 2022).
depression (1 paper, 2024). "MRM validation revealed that C1QB and SAP proteins showed significant differences between patients with depression and patients who achieved normal remission." (PMID 39424870, 2024).